FTO (FTO alpha-ketoglutarate dependent dioxygenase)
Diseases named in the same sentence as FTO in open-access papers (continued):
Sharing a sentence is not in itself a finding about the gene and the disease.
Obesity (continued). "The emergence of numerous GWA studies relating FTO SNPs with obesity/overweight across different populations motivated further research into investigating FTO physiological and pathological relevance; yet, the underlying molecular role of FTO in adipogenesis and cancer requires further research." (PMID 35409166, 2022). "- Anti-obesity (↓body weight, fat mass, visceral fat; ↓serum TC, TG, glucose; ↑basal metabolic rate) in obese humans (214 participants, 1,000 mg/day, 6 months), the presence of polymorphisms FTO might hamper these beneficial effects." (PMID 35769384, 2022). "Furthermore, obesity-associated protein [fat mass and obesity-associated protein (FTO)], which decreased significantly in POF mice, could inhibit cell apoptosis via activating autophagy." (PMID 35784556, 2022). "We reviewed Pubmed, Medline, Embase and Web of Science for MR studies published before 21 May 2020 that used at least one single-nucleotide polymorphism (SNP) in the fat mass and obesity-associated (FTO) gene as instrumental variable (IV) for body mass index, irrespective of the outcome." (PMID 35186031, 2022). "In particular, two studies demonstrated that the variants rs9939609 and rs9930506 in the first intron of the FTO gene are significantly associated with BMI, thus suggesting that the presence of these variants may increase the risk of obesity in both adults and children." (PMID 36452324, 2022). "Moreover, the impact of FTO on lipid oxidation in PCOS women might also contribute to the mechanism underlying the comorbidity of obesity and PCOS." (PMID 35144605, 2022). "FTO expression is different in underfeeding and fasting conditions and displays tissue-specific differences in mouse models of obesity, but it is not known whether these differences are the cause or the consequence of obesity." (PMID 35372458, 2021). "In addition, based on genome-wide association studies, a single nucleotide polymorphism (SNP), such as at the locus of the Fat mass and obesity-associated (FTO) gene intronic region rs1421085, can critically contribute and modify the development of thermogenic phenotype." (PMID 34895148, 2021). "However, some results link the effect of the FTO gene methylation with the risk of obesity." (PMID 34063412, 2021). "Finally, fat mass and obesity associated (FTO) and ALKBH5 have been identified as m6A erasers." (PMID 33922187, 2021). "Moreover, some studies suggested that polymorphisms at fat mass and obesity associated (FTO) gene might be significantly associated with PTC risk, while the results of some other studies were controversial." (PMID 34837923, 2021). "The FTO gene is located at chromosome 16q12.2 and contains variations in its intronic regions that may be associated with an increase in body fat, leading to a potential risk of obesity." (PMID 31947684, 2020). "Additionally, the obesity problem in humans has been linked to the FTO." (PMID 33511112, 2020). "Additionally, studies have found that the FTO polymorphisms were associated with the expression level of the IRX3 gene, which could potentially link the FTO polymorphisms with obesity by regulating metabolic rate in the adipose tissue." (PMID 32785234, 2020). "However, the relationship between FTO genotype and dietary intake seems to be very complex and many factors may have a role in this association such as the obesity, level of physical activity, serum leptin, and other dietary components." (PMID 32843047, 2020). "However, the obesity–FTO associations are reviewed well elsewhere." (PMID 33511112, 2020). "While neither our study nor the prior UK Biobank GWAS of lung function could assign a candidate gene to the FTO region variants based on colocalization with eQTL or other approaches, studies have linked obesity-related FTO variants to expression of the distal genes IRX3 and IRX532." (PMID 33057025, 2020).
Obesity (continued). "As the first obesity‐related gene identified by genome‐wide association analysis analysis, not only FTO is closely associated with obesity and tumour, but also its common variant rs9939609 may be associated with central nervous system diseases, such as brain volume loss and alcohol dependence." (PMID 33029866, 2020). "Additionally, we investigated the influence of FTO variants on theperiod of obesity onset." (PMID 32154826, 2020). "Since the presence of the FTO risk allele may lead to loss of restrain on the expression of genes related to thermogenesis and its regulation, we also looked for and found DEGs that showed higher expression in obesity-risk genotype samples." (PMID 32316277, 2020). "Finally, IRX3, which was already described as a negative and positive regulator of the development of thermogenic adipocytes, was also among the genes kept lowly expressed in DN and FTO T/T adipocytes, but became higher expressed in the adipocytes with the obesity-risk genotype." (PMID 32316277, 2020). "Therefore, the aim of our study was to evaluate whether daily macronutrient intake could modify the association between genetic variations of the FTO gene and obesity and obesity-related metabolic consequences among the Polish population." (PMID 33114268, 2020). "While the exact mechanism remains to be unraveled, it has been shown that genetic variants within the FTO gene are linked functionally to another obesity-related gene called IRX3, which promotes browning of white adipocytes, maybe a connecting link between FTO variants and obesity-related disorders." (PMID 32346024, 2020). "In recent decades, the involvement of many genes and polymorphisms in the pathogenesis of overweight/obesity have been hypothesized, such as: tumor necrosis factor-α (TNFα), interleukin (IL)-6, methylenetetrahydrofolate reductase (MTHFR) and fat mass and obesity-associated (FTO) gene." (PMID 31344895, 2019). "Given that the obesity has a strong heritable component, further genetic studies have shown that FTO encodes for an enzyme able to remove methyl groups from DNA and RNA nucleotides in vitro and human studies, emphasizing the involvement of epigenetic mechanisms in obesity." (PMID 31728912, 2019). "Given that FTO is a key obesity-associated gene and an important factor controlling feeding behavior and energy expenditure, it could be likely that metformin elicits direct actions on obesity via adiposity reduction." (PMID 31527397, 2019). "One of the most accepted hypotheses to explain the molecular mechanism takes into consideration that the expression regulation of FTO and other nearby genes (RPGRIP1L and IRX3) is a process controlled by an obesity‐associated region in intron 1 of FTO, which we also replicated in this study." (PMID 31033179, 2019). "Taking into account the findings of the previous and present studies, we can suggest an association between hypothalamic FTO and epigenetic alterations that may involve in hypoglycemia and obesity; however, further studies are required to support this suggestion." (PMID 31728912, 2019). "Ethnicity is likely to have an effect on the variation in association of FTO with inflammatory markers and investigating these variants may offer a better understanding of their role in the obesity epidemic affecting the world and particularly countries such as Kuwait and others in the Gulf region." (PMID 32076432, 2019). "Therefore, it is possible that the higher cognitive restraint observed in FTO risk allele carriers in the present study may offset FTO-mediated obesity risk in physically active individuals; but further work is required to confirm this chronically." (PMID 29686893, 2018). "Therefore, ethnicity might be an important variable regarding the role of FTO gene polymorphism in obesity development." (PMID 30338250, 2018). "However, the exact function of the FTO gene and the molecular mechanisms linking these non-coding variants with obesity remain unknown." (PMID 28738793, 2017).
Obesity (continued). "The aim of this study was to explore whether interactions between FTO rs9939609 and ABCA1 rs9282541 affect BMI and waist circumference (WC), and could explain previously reported population differences in FTO-obesity and FTO-BMI associations in the Mexican and European populations." (PMID 28464932, 2017). "Interestingly, the m6A demethylase FTO/ALKBH9 was the first human obesity susceptibility gene identified by genome-wide association studies, but the relevant nucleic acid target(s) remain unknown." (PMID 28640815, 2017). "The FTO gene may influence pathways implicated in regulation of TL, which could help to explain some of the non-consistent relationship between weight phenotype and telomere length that is observed in population studies investigating obesity." (PMID 28859657, 2017). "Additionally, FTO-variant linked obesity may be associated with altered metabolic functions through activation of downstream metabolic mediators including AMPK." (PMID 28859657, 2017). "However, there is increasing interest in ascertaining whether lifestyle factors modify the association of FTO variants and obesity; this could better provide insight into the role of diet/environmental factors in the pathogenesis of obesity." (PMID 28954439, 2017). "The obesity-associated FTO variants are located in a super-enhancer region and have been associated with DNA methylation levels, suggesting that this region may be sensitive to epigenetic effects that could mediate the interaction between FTO and PA." (PMID 28448500, 2017). "The exact mechanism by which FTO protein is linked to obesity and T2DM is still completely unknown." (PMID 28915859, 2017). "Therefore, IUGR piglets may be also a valuable model for studying early stage of predisposition to development, connected with FTO protein obesity, or type 2 diabetes development." (PMID 28757676, 2017). "Furthermore, we previously showed that changes in adiposity and metabolic response to weight loss diets varying macronutrient content were significantly influenced by several other individual genetic variants, such as those relating obesity (FTO and NPY), and type 2 diabetes (TCF7L2 and IRS1, etc.)." (PMID 28387720, 2017). "However, the molecular mechanisms by which FTO variants increase individual susceptibility to overweight and obesity remain unclear." (PMID 26726774, 2016). "Interestingly, in terms of food intake and weight control, many studies have been in agreement with not only the association between FTO genetic variants and food intake or increased appetite, but also the interaction effects of diet components with FTO SNPs on obesity risk." (PMID 26908368, 2016). "The present study shows that carbohydrate and dietary fibre intake may modify the association of the FTO SNPs, rs8050136 and rs11076023, with obesity traits, with the effect of the SNP being more pronounced among those who consumed high levels of carbohydrate and dietary fibre." (PMID 27274759, 2016). "In this study we aimed to 1) examine genetic correlations between body fat% and CRF; 2) determine whether CRF can be attributed to a genetic risk score (GRS) based on known body fat% increasing loci; and 3) examine whether the fat mass and obesity associated (FTO) locus associates with CRF." (PMID 27846319, 2016). "Similar to the findings of this previous report, since FTO SNPs have been reported to be associated with BMI, a marker of obesity, and obesity has been reported to be a strong risk factor for T2D, BMI could be considered as a collider covariate for FTO SNPs and T2D." (PMID 27820839, 2016). "Therefore, the purpose of this study is to examine whether regular PA modifies the effect of the variations in the FTO gene on obesity risk, as measured by BMI, fat mass, hip circumference, and waist circumference in a Latino population." (PMID 26908368, 2016).
Obesity (continued). "Moreover, there is increasing evidence that the FTO genetic susceptibility to obesity can be modulated by lifestyle factors, and that PA, for example, may attenuate the effects of the FTO genotype on obesity-related traits." (PMID 26851191, 2016). "In the present study, we examined whether dietary intake and physical activity levels modified the association of the two commonly studied FTO single nucleotide polymorphisms (SNPs) with obesity-related traits and T2D in 1,618 individuals in the Chennai Urban Rural Epidemiology Study (CURES)." (PMID 27274759, 2016). "This FTO risk allele may contribute to obesity by decreasing satiety responsiveness." (PMID 27196523, 2016). "Importantly, a disease-associated SNP may not necessarily influence the nearest gene, as is the case for obesity-associated SNPs within the FTO gene, which appear to influence the expression of a more distal gene, IRX3." (PMID 27935966, 2016). "However, FTO has multiple functions other than associations with obesity." (PMID 26727661, 2016). "Furthermore, a very recent study observed a parent-of-origin effect of FTO SNPs, albeit in a very small population in Germany, suggesting that these parent-of-origin effects may modulate the association between FTO SNPs and obesity." (PMID 26788058, 2015). "Thus, studies on pathways downstream of TCF3 may pave the path for better understanding the mechanism underlying associations of FTO with obesity." (PMID 25647475, 2015). "The aim of the current study was to analyze the association of common variants in Fat Mass and Obesity associated (FTO) gene with obesity in Pakistan, to find out the effect of the selected SNPs on anthropometric and biochemical traits, and to observe whether these variants act synergistically." (PMID 26357660, 2015). "Therefore, the obesity-risk variant of FTO might be involved not only in fat mass accumulation but also in constitution typing." (PMID 25888059, 2015). "The BMI was adjusted in the association between the FTO variant and SC types, since the rs7193144 is strongly linked with rs9939609 and rs8050136 variants in the Asian HapMap population which variants are well known to contribute to obesity and diabetes through affecting BMI." (PMID 25888059, 2015). "In addition, our model suggests that for males that have lived with T2D for less than 11 years, if they are heterozygous at the obesity and T2D candidate gene, FTO (fat mass and obesity associated), they are more likely to develop DN when their LDL levels exceed 100 mg/dl." (PMID 25707942, 2015). "Following this discovery, FTO was found to encode an enzyme involved in control of body weight and metabolism based on evidence from FTO-deficient mice and from a study of mouse overexpression phenotypes in which additional copies of the gene led to increased food intake and obesity." (PMID 25473428, 2014). "In addition, FTO gene variation might influence the baseline lipid oxidation to increase the obesity risk in PCOS." (PMID 24466303, 2014). "Considering that the development of liver fibrosis is strongly associated with overweight/obesity, insulin resistance and steatosis, we think that the association between the FTO rs9939609 polymorphism and liver fibrosis might be mediated by the metabolic disorders related to CHC." (PMID 25367448, 2014). "Therefore, the current study was designed to examine the associations of FTO rs9939609 with the risk of obesity and obesity-related metabolic traits in 3924 Chinese Han children and adolescents (7–18 years of age) living in the northern, central and southern regions of China." (PMID 25110886, 2014). "In addition to obesity, the FTO rs9939609 polymorphism was found to be associated with type 2 diabetes in Vietnamese (OR per A allele = 1.61, 95% CI: 1.06-2.44), South Asians (OR per A allele = 1.18, 95% CI: 1.07-1.30), and Chinese (OR for allele A = 1.31, 95% CI: 1.10-1.55)." (PMID 25377722, 2014).
Obesity (continued). "Thus, it is likely that FTO has an important role in the sex- and ethnic-specific risk of obesity." (PMID 24879436, 2014). "The FTO rs9939609 single nucleotide polymorphism (SNP) variant is of particular interest because it has the strongest known effect on increased BMI, and its association with BMI and obesity-related phenotypes has been confirmed by independent studies in large Caucasian populations." (PMID 25110886, 2014). "According to this study, the top hit within the intron 1 of FTO gene was the rs1421085 although all the SNPs in high linkage disequilibrium (LD) with this variant were also strongly associated with BMI, including the rs9939609 the most replicated that increase 31% the risk of obesity." (PMID 24267414, 2013). "Thus, a gain-of-function effect is suggested for the pathogenic role of FTO in human obesity." (PMID 23825611, 2013). "Exercise may attenuate the association between FTO A/T polymorphism and obesity related-traits." (PMID 23573268, 2013). "Besides obesity, FTO also confers risk to T2DM, although this association may be independent of BMI in East and South Asian." (PMID 23840863, 2013). "Of the many found associated, the FTO rs9939609 single nucleotide polymorphism (SNP), located in the first intron, is of particular interest since it was the first to be found to be associated with obesity and has been constantly replicated through independent studies of large Caucasian populations." (PMID 22454631, 2012). "Another possible explanation is that genotypes including the FTO gene which impacts appetite may influence control over food intake and choices resulting in children from obese families having a greater predisposition for obesity." (PMID 22912886, 2012). "The goal of the present study was to further clarify whether genetic variation in FTO, that is similar to or in linkage disequilibrium (LD) with the SNPs previously reported to be associated with obesity-related measures or AD endophenotypes is associated with AD." (PMID 23251365, 2012). "As obesity itself is in some cases also associated with lower brain volume as well as cognitive deficits, FTO may be one of the genes bridging body weight dysregulation and other physiological abnormalities that oftentimes accompany abnormally low or high body weight." (PMID 22087873, 2011). "Thus, we demonstrate that the currently known major common variants related to obesity overlap to a substantial degree between children and adults confirming previous observations for FTO, MC4R, TMEM18, NEGR1 and extending this observation to SEC16B, BDNF and BCDIN3D;." (PMID 20421936, 2010). "Furthermore, both models suggest that alleles associated with increased risk of obesity will cause up- or dysregulation of FTO and that inhibition of FTO might protect against obesity." (PMID 20381893, 2010). "In this study, all of the FTO polymorphisms were associated with elevated risk for diabetes and obesity in white participants, while addition of the rs1421085 C allele was a determinant of increased susceptibility to obesity in African-Americans but conferred a protective effect against diabetes." (PMID 20502638, 2010). "This study reveals the multi-factorial origin of obesity and indicates that although the FTO gene may put some children at greater risk of obesity, encouraging a low dietary energy density may be an effective strategy to help all children avoid excessive fat gain." (PMID 19259258, 2009). "However, several larger studies of Chinese, Malay, Korean and Japanese populations as well as Canadians of South Asian origin and Inuit demonstrated associations between FTO polymorphisms and BMI/obesity with similar effect sizes compared to populations of European ancestry." (PMID 19265514, 2009).